DPY30 (dpy-30 histone methyltransferase complex regulatory subunit)
Description:
As part of the MLL1/MLL complex, involved in the methylation of histone H3 at 'Lys-4', particularly trimethylation. Histone H3 'Lys-4' methylation represents a specific tag for epigenetic transcriptional activation. May play some role in histone H3 acetylation. In a teratocarcinoma cell, plays a crucial role in retinoic acid-induced differentiation along the neural lineage, regulating gene induction and H3 'Lys-4' methylation at key developmental loci. May also play an indirect or direct role in endosomal transport.
Synonyms: Saf19; HDPY-30; Cps25
Tractability: Small molecule: a structure with a bound ligand is known; a high-quality ligand is known. PROTAC: UniProt records ubiquitination sites on it; ubiquitination databases record sites on it; its protein half-life has been measured; a small molecule that binds it is known.
Gene: Protein-coding gene on chromosome 2 (31,867,809 to 32,039,809, reverse strand). Ensembl gene ENSG00000162961.
Subcellular location: Nucleus; Golgi apparatus, trans-Golgi network
Subcellular location (Human Protein Atlas): Nucleoplasm; Golgi apparatus
Pathways (Reactome):
Gene expression (Transcription): Epigenetic regulation of gene expression by MLL3 and MLL4 complexes; Formation of WDR5-containing histone-modifying complexes; MLL4 and MLL3 complexes regulate expression of PPARG target genes in adipogenesis and hepatic steatosis; RUNX1 regulates genes involved in megakaryocyte differentiation and platelet function
Developmental Biology: Activation of anterior HOX genes in hindbrain development during early embryogenesis; Differentiation of naive CD4+ T cells to T helper 2 cells (Th2 cells)
Signal Transduction: Deactivation of the beta-catenin transactivating complex; Formation of the beta-catenin:TCF transactivating complex
Chromatin organization: PKMTs methylate histone lysines
Disease: Loss of Function of KMT2D in MLL4 Complex Formation in Kabuki Syndrome
Immune System: Regulation of PD-L1(CD274) transcription
Gene Ontology:
Molecular function: identical protein binding; protein binding; protein homodimerization activity
Biological process: endosomal transport; transcription initiation-coupled chromatin remodeling
Cellular component: Golgi apparatus; histone methyltransferase complex; MLL1 complex; MLL1/2 complex; MLL3/4 complex; nucleoplasm; nucleus; Set1C/COMPASS complex; trans-Golgi network
Genetic constraint (gnomAD): Loss-of-function variants: 6 observed, 15.85 expected, observed/expected ratio (o/e) 0.38, 90% interval 0.21 to 0.75. The upper end of that interval is the gene's LOEUF score, 0.75, which puts it in group 3 of 6, group 1 being the genes least tolerant of losing a copy. Missense variants: 72 observed, 114.36 expected, observed/expected ratio (o/e) 0.63, 90% interval 0.52 to 0.77. Synonymous variants: 39 observed, 40 expected, observed/expected ratio (o/e) 0.97, 90% interval 0.75 to 1.27.
Homologues: Orthologues: chimpanzee DPY30 (100% identical), macaque DPY30 (100% identical), pig DPY30 (100% identical), dog DPY30 (99% identical), guinea pig DPY30 (99% identical), mouse Dpy30 (98% identical), rat Dpy30 (98% identical), tropical clawed frog dpy30 (82% identical), zebrafish dpy30 (75% identical).